IL5 (interleukin 5)
Diseases named in the same sentence as IL5 in open-access papers (continued):
Sharing a sentence is not in itself a finding about the gene and the disease.
asthma (continued). "Studies have indicated that IL-5 might augment neutrophil responses during allergic inflammation, potentially exacerbating tissue damage and contributing to the pathophysiology of conditions such as asthma." (PMID 41259376, 2025). "However, studies in asthma and other inflammatory diseases suggest that genetic variations in cytokines such as IL-5, IL-4, IL-13, and TNF may influence responses to biologic therapies." (PMID 40149465, 2025). "Furthermore, sputum total IgE may also serve as a potential biomarker for guiding anti‐IL‐5 therapy in patients with severe asthma, with higher levels of sputum total IgE possibly predicting better responses to anti‐IL‐5 therapy." (PMID 39757370, 2025). "Future work could further investigate whether altered levels of IL-5 and IL-9 can be used as biomarkers of asthma development, and further explore the potential mechanism of action of IL-5 and IL-9 in asthma, and evaluate their potential for clinical prevention and treatment of asthma." (PMID 39175819, 2024). "Thus, in contrast to the Type 2 (T2 or eosinophilic) type of asthma which was mediated by IL-4, IL-5, and IL-13, the profile of the inflammatory mediators with high levels of IL-6, CXCL8, and IFNγ after TLR stimulation mirrored that of the non-T2 endotype of asthma." (PMID 39614276, 2024). "It is possible that a medication that targets IL-5 might successfully reduce asthma episodes linked to eosinophilia without unduly affecting other aspects of host health because IL-5 seems to be a less pleiotropic cytokine than others." (PMID 38535313, 2024). "Notably, treatment with BXM significantly ameliorated asthma symptoms, including less lung inflammation, mucus secretion, and the generation of Th2 cytokines (IL-5, IL-13, and IL-4), which were dramatically attenuated by anti-VISTA monoclonal antibody treatment." (PMID 38340268, 2024). "RSV infection also induces STAT1-dependent IFNγ production by NK cells, while STAT1-deficient mice exhibit increased IL-5+ and IL-13 + ILC2s and IL-17A + ILC3s in the lung in response to RSV infection, suggesting that ILCs play a role in RSV infection beyond impacting asthma pathology." (PMID 38684766, 2024). "Thus, the implementation of anti-IL-5 therapy, already used in asthma, could be beneficial for patients with other eosinophilic diseases and is a promising field for scientists." (PMID 39062104, 2024). "Furthermore, IL-5 contributes to eosinophil activation and bronchial hyperreactivity." (PMID 39483467, 2024). "Also, in patients with asthma and obesity, anti-IL-5 biologics may have limited effectiveness due to their specific effects on eosinophil maturation, activation, survival, and recruitment to the airway." (PMID 38259298, 2023). "Therefore, inhibiting IL-5 or IL-5 signaling seems to be a good option for asthma." (PMID 36845128, 2023). "Furthermore, in patients with T2-high asthma, such a complex process may result in IgE, IL-13, IL-4, IL-5, and eosinophil responses, covering more than 50% of asthma endotypes." (PMID 38203353, 2023). "Likewise, stamen extract of Mesua ferrea L. (Calophyllaceae) from the Calophyllaceae family and root extract of Clerodendrum serratum of the genus Clerodendrum is reported to ameliorate allergic asthma through the modulation of few asthma-associated cytokines like TNF-α, IL-5, and IL-4." (PMID 37251328, 2023). "Interestingly, the same biologics—namely anti-IgE, anti–IL-5, and anti–IL-4Rα–have been recently approved for the treatment of severe CRSwNP (while dupilumab was approved first in severe CRSwNP, before asthma), further increasing the relevance of integrating UAD in the management of (severe) asthma." (PMID 37035303, 2023). "However, whether these IL-5-targeting agents for severe asthma suppress EGPA development remains unclear." (PMID 37762936, 2023).
asthma (continued). "Moreover, it had satisfactory performance in diluted sputum and clinical subjects with asthma, which could achieve sensitive detection of the airway inflammatory factor IL-5." (PMID 38149176, 2023). "Furthermore, in a human study of asthma, choline therapy also reduced peripheral IL-5 levels." (PMID 36831213, 2023). "Therefore, IL-5 and its receptor appear to be proper therapeutic targets for biologic drugs (mepolizumab, reslizumab, benralizumab) that are able to inhibit eosinophilic inflammation and airway remodeling in both asthma and nasal polyposis." (PMID 37240477, 2023). "Although ADNP has not been identified as a common factor in asthma susceptibility, unlike IL-4, IL-5, and IL-13, it was reported among a subset of genes that were differentially expressed by CD4+ lymphocytes and that predicted more atopic from less atopic children." (PMID 37285842, 2023). "Interestingly, either the overexpression of Nr1d1 or the treatment with its ligand (SR9011) protected mice against lung inflammation in an asthma model (as shown by lung histology, reduced histological scores, IL-4-, IL-5-, and IL-13-levels, as well as reduced GATA3 expression) [37••]." (PMID 36520269, 2023). "Furthermore, previous research in asthma patients proved exogenous supplementary choline as an anti-inflammatory factor inducing lowered levels of pro-inflammatory cytokines, including IL-4, IL-5, and TNF-α, which are also involved in T1D." (PMID 40303249, 2023). "Finally, the clinical efficacy of anti-IL-5-targeted therapy at approved doses for severe asthma (benralizumab 30 mg, mepolizumab 100 mg) and high (benralizumab 100 mg, mepolizumab 300 mg) doses were included in the integrated analysis of COPD patients with increased peripheral blood eosinophils." (PMID 35756113, 2022). "Since IL-4, IL-5, IL-10, IL-17, and IL-33 would not be measured in peripheral blood samples, we think it is not feasible to use these cytokines in clinical practice or in the research of the underlying mechanisms of the asthma phenotypes." (PMID 36326393, 2022). "However, for severe asthma new biological therapies have been introduced to inhibit molecular pathways leading to severe symptoms; in particular, mepolizumab and benralizumab act against the IL-5 pathway." (PMID 35453511, 2022). "This allows us to assume that steady-state rEOS-like cells might be less activated, and the bronchial allergen challenge, related to an acute asthma episode and a release of various proinflammatory cytokines, enhanced their response to IL-5 or GM-CSF and proliferative effects on ASM cells." (PMID 36497064, 2022). "Moreover, the IL-5-anchored CCAR-T cells maintained effective control of asthma-related conditions for up to three months, including the eosinophil levels in BALF, peripheral blood and bone marrow, IL-5 levels in BALF as well as the inflammatory infiltration in the airway." (PMID 35973984, 2022). "IL-5 is mainly secreted by activated Th2 cells, mast cells, NK cells, NKT cells, and eosinophils; is involved in the differentiation, proliferation, migration, activation, and survival of eosinophils; and is associated with increased eosinophils and asthma severity." (PMID 36016177, 2022). "A study assessing the impact of anti-interleukin-5 therapy (mepolizumab) on objectively measured cough showed significant reductions in cough frequency after 6 months of therapy, supporting the concept that targeting eosinophilic inflammation in severe asthma has an impact on cough." (PMID 35777770, 2022). "The three subfamilies of MAPKs have been involved in the pathogenesis of asthma, and JNK and P-38, in particular, are more closely associated with asthmatic airway inflammation, which can cause high expression of downstream factors such as IL-6, IL-1β, and IL-4 and IL-5, respectively." (PMID 36081945, 2022).
asthma (continued). "In conclusion: IL-5 and GM-CSF promote the proliferative properties of iEOS-like and rEOS-like eosinophils; however, the effect of only IL-5 may be related to the expression of its receptors in asthma patients." (PMID 36497064, 2022). "This association with asthma in the PPI network is also consistent with benralizumab’s MoA, that is, benralizumab inhibits the binding between interleukin-5 and the alpha subunit of interleukin-5 receptor and thus blocks the interleukin-5-induced eosinophil-mediated inflammatory response." (PMID 35338014, 2022). "However, eosinophils are still implicated in the pathophysiology of asthma and both allergic and non-allergic eosinophilic asthma is driven by IL-5." (PMID 36232470, 2022). "Numerous previous studies have shown that eosinophilic asthma is mainly characterized by IgE and Th2 cytokines (IL-4, IL-5, etc.), whereas neutrophil asthma is mainly characterized by Th17 cytokines (IL-17, IL-6, etc.), which are involved in the development of steroid-resistant asthma." (PMID 36081945, 2022). "EoE shares several commonalities with asthma, including aberrant eosinophil activation and recruitment, the prominence of IL-13 and epithelial dysfunction, and overlapping therapeutic targets such as the IL-4 receptor, IL-13, thymic stromal lymphopoietin, IL-5, and IL-5R." (PMID 35082127, 2022). "Despite all these treatments, severe asthma can remain uncontrolled, thus requiring adjunctive biological therapies based on the use of monoclonal antibodies directed against immunoglobulins E (IgE), interleukin 5 (IL-5), IL-5 receptor, or interleukin-4 (IL-4) receptor." (PMID 33922072, 2021). "In addition, kaempferol treatments attenuated the Th2-driven allergic airway disease in an experimental model of asthma induced by OVA challenge by decreasing the production of IL-5 and IL-13 and ameliorating airway hyperresponsiveness induced by OVA challenge." (PMID 34552650, 2021). "Second, although we conducted the comparison between anti-IL-5 therapy in eosinophilic COPD and in asthma, further RCTs that compare the anti-IL-5 therapy with ICS in eosinophilic COPD are needed, which may allow us to better determine the efficacy of anti-IL-5 therapy in eosinophilic COPD." (PMID 34795588, 2021). "In the three treated groups of asthma and also, allergic rhinitis (Co-Q10 received groups, Co-Q10 and O-3 received groups, Co-Q10 and Mg-S received groups), reverse trend was found and significantly reduced IL-4, IL-5, IL-13, and restored the IFN-γ levels (P < 0.05)." (PMID 33743807, 2021). "Recently, the use of anticholinergics and biological antibodies (anti-IgE/anti-IL5) was approved depending on the severity of this disease; the use of any combination reduces inflammatory biomarkers and improves the symptoms (Global Initiative for Asthma, 2020)." (PMID 34055794, 2021). "Finally, asthma-related Th2 cytokines such as IL-4, IL-5, and IL-13 can induce EGFR expression, while cytokines produced by activated eosinophils such as IL-3 and IL-5 can induce TGF-α production by epithelial cells and subsequently induce mucins production through EGFR signaling." (PMID 34248677, 2021). "Additionally, if benefit is demonstrated, a potentially larger market may exist for a therapy whose initial trials used a lower inclusion value, as witnessed by the varying criteria for use of FDA-approved anti-IL-5 drugs in asthma." (PMID 34739571, 2021). "Furthermore, the high FeNO levels (> 25 ppb) showed by our patients at baseline, despite high doses of ICS, may be a further evidence of severe asthma IL-5-driven." (PMID 33750842, 2021). "Therefore, increased levels of IL-13, IL-5, and IL-4 mediate the development of asthma." (PMID 34258300, 2021). "Thus, given the mixed outcomes of targeting IL-5/eosinophils and the potential for the involvement of other inflammatory immune cells in asthma pathogenesis, there remains an unmet need for better asthma treatments, particularly in terms of exacerbation prevention." (PMID 35386999, 2021).
asthma (continued). "For patients with non-allergic eosinophilic asthma, who have obvious characteristics of eosinophilic granulocyte increase, anti-interleukin-5/5R treatment or oral corticosteroids may be given in future when asthma is just partly controlled or even uncontrolled." (PMID 33941235, 2021). "Further, among males with asthma, lower levels of TH1 cytokines were statistically significantly associated with higher levels of PFDA (IL-2 only), and higher levels of TH2 cytokines were statistically significantly associated with higher levels of PFOA (IL-4 and IL-5) and PFBS (IL-5 only)." (PMID 34712855, 2021). "Allergic asthma is the most common asthma phenotype, and Th2 immunity is classically thought to be important in mediating bronchial inflammation during allergic asthma by cytokines such as IL-4, IL-5, and IL-13 produced from CD4 + Th2 cells and innate lymphoid cells." (PMID 34194525, 2021). "Moreover, elevated leukocyte translation into the airways, particularly eosinophils, is a critical phenomenon in the OVA-induced asthma mouse model, correlated with specific chemokines, such as eotaxin, and also regulated by Th2-secreted cytokines such as IL-5." (PMID 33919400, 2021). "Indeed, further studies that aim to assess the impact of different mAbs on specific asthma phenotypes according to the levels of IgE, IL-4, IL-5, and IL-13 may further optimize the efficacy of the current mAbs for the treatment of severe asthma." (PMID 34281184, 2021). "Indeed, recent studies have shown that when monoclonal anti-IgE omalizumab, or the anti-IL-5 mepolizumab are added to the asthma therapy, there is a reduction in the frequency of asthma exacerbation and hospitalization and the necessity for higher doses of ICS." (PMID 33101014, 2020). "Plasma levels of CCL5 and IL-5 or eosinophil counts in the peripheral blood may not be useful diagnostic biomarkers to evaluate airway inflammation and monitor asthma severity." (PMID 32467785, 2020). "Expression profiles reassembled in nasal and bronchial brushings, were specific to asthma independently of atopic status, and clustering analysis identified Th2-high and low subjects differentiated by expression of 70 genes (such as IL-13, IL-5, periostin, CLCA1, SERPINB2)." (PMID 32292784, 2020). "The classical form of asthma is considered to be mediated by T helper cell type 2 (Th2) cells and is characterized by eosinophilic inflammation, immunoglobulin (Ig) E reactivity, and the predominance of Th2 cytokines such as interleukin (IL)-4, IL-5, and IL-13." (PMID 32580518, 2020). "Thus, ginseng can suppress IgE, IL-4, and IL-5 expression and Th2-to-Th1 cell ratio through the modulation of mast cell, basophil, and eosinophil activation, resulting in the attenuation of AD, allergic rhinitis, asthma, and pruritus." (PMID 32326081, 2020). "However, unlike IL-13 and IL-5, which are increased in individuals with asthma, COX-2 deficiency has been linked to increased severity of asthma progression." (PMID 33022979, 2020). "The unique task of interleukin (IL)-5 in producing, activating, and localizing eosinophils has led to speculation that it represents the next primary goal for therapeutic intervention in asthma, chronic obstructive pulmonary disease, and other eosinophilic diseases." (PMID 33321726, 2020). "In addition, the analysis of CCL5 and IL-5 in the sputum was outside the scope of this work, and thus, consequent studies should investigate the probability that sputum cytokine expression is a good indicator of asthma activity." (PMID 32467785, 2020). "Moreover, in T2-high asthma IL-5 induces eosinophil adhesion to and migration in the extracellular matrix by favoring the interaction of eosinophils with periostin, a matricellular protein whose enhanced expression is associated with eosinophil trafficking toward bronchi." (PMID 31920718, 2019).
asthma (continued). "Compared with helper T 2 (Th2) cytokines [IL-1β, IL-4, IL-5, and tumor necrosis factor-α (TNF-α)], helper T 1 (Th1) cytokines (IFN-γ and IL-12) are associated to antagonism of immunoglobulin E (IgE) synthesis and Th2 cell responses to restrain the progress of asthma." (PMID 31330806, 2019). "Many studies confirmed that a broad spectrum of inflammatory mediators, such as IL-4, IL-5, and IL-13, synthesized and released by activated inflammatory cells, particularly Th2 cells, eventually induce airway mucus hypersecretion which is essential for the pathogenesis of asthma." (PMID 31073274, 2019). "The evidence of IL-25-mediated Th2 cell differentiation, increase in production of IL-4, IL-5, and IL-13, elevated IgE and IgG levels, eosinophil infiltration, goblet cell hyperplasia and mucus hypersecretion, provided the proof for the role of IL-25 into asthma pathogenesis." (PMID 31355170, 2019). "Thus, the inhibitory effect of A. muciniphila on this eosinophil population may have clinical relevance given the established relationship between IL-5 levels, eosinophils and asthma exacerbations." (PMID 31836714, 2019). "Th2-cell derived cytokines including IL-4, IL-5, and IL-13 could contribute to long-term airway hyper-responsiveness and smooth muscle growth, which have significant impact on the decline of lung function and the development of asthma severity." (PMID 30691461, 2019). "Typically in asthma, cytokines released by Type 2 T helper (Th2) cells including interleukin-4 (IL-4), interleukin-5 (IL-5), and interleukin-13 (IL-13) as well as cytokines released by Type 1 T helper (Th1) cells such as interferon-gamma are considered to be the main cytokines triggered in asthma." (PMID 30333747, 2018). "Serum total IgE is used in practice to verify that a patient with severe allergic asthma could be a candidate for omalizumab therapy and blood eosinophils count (usually ≥300 cells/μL) to prescribe biological agents such as anti-IL5 antibody in the eosinophilic refractory severe asthma." (PMID 30598830, 2018). "Therefore, eosinophils are likely to contribute to the development of asthma exacerbation through several mechanisms, including activation by Th2 cytokines, such as IL-5 or GM-CSF or by virus infection-related proteins, such as CXCL10, and interaction with other cells, such as neutrophils." (PMID 30323811, 2018). "This type of asthma is thought to arise from an imbalance in T helper type I (Th1)-Th2 immune regulation, resulting in increased levels of the Th2 cytokines interleukin (IL)-4, IL-5, and IL-13, which have been proven to be important drivers of allergic airway inflammation in asthma." (PMID 29867963, 2018). "Establishing the efficacy of eosinophil-depleting antibodies in asthma turned out to be challenging, with a particularly long interval between the first clinical trial (published in 2000) and regulatory approval of the first anti-IL-5 antibody for severe eosinophilic asthma in 2015." (PMID 29682504, 2018). "However, it was interesting to note that the treatments appeared to act slightly differently, since PDT decreased the number of eosinophils and IL-5 in the mice without asthma and caused less bone resorption as well." (PMID 29145431, 2017). "Simultaneous inhibition of IL-3, IL-5 and GM-CSF may benefit asthma control." (PMID 28106744, 2017). "However, there was a significant decrease in IL-5 (b = -0.74, 95%CI:-1.39;-0.09, p = 0.03), an increase in asthma-related quality of life over time (b = 0.27, 95%CI:0.15;0.40, p<0.001) and a reduction in sickness behaviour (b = -0.10, 95%CI:-0.20;0.00, p = 0.04)." (PMID 28915273, 2017). "However, Oral application Lactobacillus rhamnosus GG inhibited allergic sensitization and airway disease in a murine model of asthma by induction of Treg cells, associated with a parallel suppression of the classical Th1-related cytokine (IFN-γ) and Th2-related cytokines (IL-4 and IL-5)." (PMID 28199353, 2017).